ERLIN2 (ER lipid raft associated 2)
Diseases named in the same sentence as ERLIN2 in open-access papers (continued):
Sharing a sentence is not in itself a finding about the gene and the disease.
Spastic paraplegia (3 papers, 2017 to 2024). Complete loss of the ability to move the lower limbs accompanied by spasticity of the lower limbs. "In addition, a dominant form of pure HSP was lately related to a heterozygous mutation in ERLIN2, which underlines the complexity of the ERLIN2 mutation in spastic paraplegia (SP) phenotype." (PMID 34572057, 2021). "A Gly50Val substitution in ERLIN1 has been implicated in autosomal recessive SPG62, whereas His50Tyr (ClinVar ID: 947803) and Arg36Lys (ClinVar ID: 1720746) in ERLIN2 have been reported as a variant of unknown significance in individuals with spastic paraplegia." (PMID 38782601, 2024).
breast tumor (2 papers, 2013 to 2015). "The xenografted ERLIN2-knockdown breast tumors displayed diminished sizes at 7 weeks after the transplantation." (PMID 27462423, 2015).
juvenile primary lateral sclerosis (2 papers, 2015 to 2024). Juvenile primary lateral sclerosis (JPLS) is a very rare motor neuron disease characterized by progressive upper motor neuron dysfunction leading to loss of the ability to walk with wheelchair dependence, and subsequently, loss of motor speech production. "Besides ALS2, juvenile primary lateral sclerosis (JPLS) has also been linked to ERLIN2 variants." (PMID 38276084, 2024).
lung adenocarcinoma (2 papers, 2020 to 2024). A carcinoma that arises from the lung and is characterized by the presence of malignant glandular epithelial cells. "Relationship between endoplasmic reticulum lipid raft-associated protein 2 (ERLIN2) expression level and clinicopathological variables and in lung adenocarcinoma patients." (PMID 33424830, 2020). "In lung adenocarcinoma (LUAD), the molecular function of ERLIN2 and the correlation between ERLIN2 and tumor-infiltrating immune cells have been unclear." (PMID 33424830, 2020).
astrocytoma (1 paper, 2020). "Conversely, ERLIN2 knockdown enhanced the apoptosis of astrocytoma cells as detected by flow cytometry analysis and TUNEL assay." (PMID 32883232, 2020). "The following functional assays manifested that down-regulated ERLIN2 hindered astrocytoma cell proliferation by applying EdU and CCK8 assays." (PMID 32883232, 2020). "More importantly, the impacts of SNHG17 down-regulation on the malignant behaviors of astrocytoma cells were counteracted by overexpressed ERLIN2 or inhibited miR-876-5p." (PMID 32883232, 2020). "In conclusion, our study found that SNHG17 promoted the proliferation, migration, invasion and stemness of astrocytoma cells via targeting miR-876-5p/ERLIN2 pathway." (PMID 32883232, 2020). "Likewise, the migratory and invasion capacities of astrocytoma cells were repressed by ERLIN2 silence." (PMID 32883232, 2020). "Subsequently, we selected out ERLIN2 as a target of miR-876-5p in astrocytoma cells." (PMID 32883232, 2020). "However, the detailed significance of SNHG17/miR-876-5p/ERLIN2 axis in chemoresistance of astrocytoma cells as well as in clinic practice needs to be further discussed and analyzed in the future." (PMID 32883232, 2020). "Additionally, miR-876-5p overexpression decelerated the biological processes of astrocytoma cells, so did ERLIN2 knockdown." (PMID 32883232, 2020). "In this study, we detected that ERLIN2 was also up-regulated in astrocytoma cells." (PMID 32883232, 2020). "In a word, ERLIN2 targeted by miR-876-5p facilitated the malignancy in astrocytoma." (PMID 32883232, 2020). "Subsequently, we analyzed the effects of ERLIN2 on the biological behaviors of astrocytoma cells." (PMID 32883232, 2020). "Finally, we implemented rescue assays to validate the effectiveness of SNHG17/miR-876-5p/ERLIN2 axis in astrocytoma cells." (PMID 32883232, 2020). "Altogether, SNHG17 could facilitate malignancy in astrocytoma through targeting miR-876-5p/ERLIN2 axis." (PMID 32883232, 2020). "Finally, rescue assays were applied to illustrate the function of SNHG17/miR-876-5p/ERLIN2 axis in astrocytoma cells." (PMID 32883232, 2020). "RT-qPCR revealed that ERLIN2 was up-regulated in astrocytoma cells compared to NHA." (PMID 32883232, 2020). "SNHG17 could induce the progression of astrocytoma by sponging miR-876-5p to elevate the expression of ERLIN2." (PMID 32883232, 2020). "Moreover, the rescue assays revealed that ERLIN2 overexpression or down-regulation of miR-876-5p could reverse the impacts of SNHG17 silence on the function of astrocytoma cells." (PMID 32883232, 2020). "Interestingly, here we also found that SNHG17/miR-876-5p/ERLIN2 axis also contributed to the resistance of astrocytoma cells to temozolomide (TMZ), a routinely-used drug for treating patients with gliomas including astrocytoma." (PMID 32883232, 2020).
cervical spondylosis (1 paper, 2021). "It was confusing to determine whether his spastic paraplegia symptoms were caused by cervical spondylosis or by ERLIN2 gene mutation." (PMID 34734492, 2021).
cognitive decline (1 paper, 2020). "One example entails mutations in ER lipid raft-associated protein 2 (ERLIN2), which result in autosomal recessive pure as well as complex forms of HSP associated with cognitive decline (SPG18), and autosomal dominant pure HSP." (PMID 31848577, 2020).
Cognitive impairment (1 paper, 2020). Abnormal cognition is characterized by deficits in thinking, reasoning, or remembering. "For example, loss of function of Erlin1 and Erlin2, mutated in SPG62 and SPG18, respectively, are responsible for early onset autosomal recessive HSP associated with cognitive impairment." (PMID 32180696, 2020).
depression (1 paper, 2017). "Future studies on ERLIN2 function using various techniques (e.g., genetically engineered mice) will help elucidate the role of this gene in depression." (PMID 28596527, 2017).
epilepsy (1 paper, 2024). A brain disorder characterized by episodes of abnormally increased neuronal discharge resulting in transient episodes of sensory or motor neurological dysfunction, or psychic dysfunction. "Like other genes involved in HSP complicated forms (mainly AR), ERLIN2 is considered an epilepsy-associated gene." (PMID 38607533, 2024).
influenza infection (1 paper, 2023). "To determine how Usp25-Erlin1/2 restricted influenza infection, we first generated shRNA-mediated depletions of Erlin1, Erlin2, and a combination of Erlin1/2." (PMID 37683630, 2023).
lung carcinoma (1 paper, 2021). "The results indicated that METTL8 and ERLIN2 were significantly and negatively correlated with the prognosis of lung cancer patients." (PMID 33816462, 2021).
lymph node metastasis (1 paper, 2020). "Our results also indicated that the expression levels of ERLIN2 were correlated with histological grade, TNM stage, and lymph node metastasis in LUAD patients." (PMID 33424830, 2020). "Moreover, the expression levels of ERLIN2 were correlated with histological grade (P = 0.044), TNM stage (P = 0.01), and lymph node metastasis (P = 0.038)." (PMID 33424830, 2020).
melanoma (1 paper, 2019). A malignant, usually aggressive tumor composed of atypical, neoplastic melanocytes. "In addition to mitochondrial membrane proteins, HLA-DR (a plasma membrane protein) and Erlin2 (an endoplasmic reticulum membrane protein) were also highly expressed in melanoma metastatic tissue-derived EVs." (PMID 31497264, 2019).
Pan (1 paper, 2020). "By employing starBase, ERLIN2, HIGD2A and LMN1 were predicted as probable targets of miR-876-5p in line with following conditions: strict stringency> = 5, high stringency> = 3, Pan Cancer 4 types." (PMID 32883232, 2020).
uremia (1 paper, 2024). A clinical syndrome associated with the retention of renal waste products or uremic toxins in the blood. "For genes with stable expression in uremia, we overlapped the genes obtained by LASSO and SVM-RFE algorithms to obtain three genes, including ZBTB2, APC, and ERLIN2." (PMID 39328595, 2024).
virus infection (1 paper, 2017). "Regardless of the mechanism, the release step is required for B12’s mobilization into the foci where it promotes virus infection as artificially locking B12 to Erlin2 prevents these downstream events from occurring." (PMID 28614383, 2017).
cancer (12 papers, 2012 to 2026). A tumor composed of atypical neoplastic, often pleomorphic cells that invade other tissues. "Apparently, the association of ERLIN2 with microtubules is consistent with the role of ERLIN2 in aiding cancer cell adaptation to cellular stress and cytosolic lipid droplet storage." (PMID 27462423, 2015). "This notion is supported by the evidence that ERLIN2 knockdown can significantly suppress cancer cell proliferation and malignancy." (PMID 27462423, 2015). "Next, we tested if amplification and over expression of ERLIN2 enhances the resistance to a variety of stressors to promote cancer cell survival." (PMID 22681620, 2012). "Therefore, the present study tentatively suggests that ERLIN2 is a cancer suppressor gene and CDK5RAP3 is an oncogene." (PMID 38643190, 2024). "Having established the roles of ERLIN2 in stabilizing microtubules and Cyclin B1 complex, we asked whether downregulation of ERLIN2 could affect cancer cell proliferation and malignancy." (PMID 27462423, 2015). "Importantly, knockdown of ERLIN2 in SUM-44 and SUM-225 cells also suppressed anchorage-independent growth in soft agar, one of the hallmark characteristics of aggressive cancer cells." (PMID 22681620, 2012). "Moreover, the protein composition, including cancer-associated markers such as MT-CO2, COX6c, SLC24A22, HLA-DR, and Erlin2, was highly consistent between EVs derived from fresh and frozen tissues, with no relevant enrichment of intracellular or mitochondrial contaminants in frozen-derived EVs." (PMID 42169004, 2026). "In this study, it was initially clarified that ERLIN2 is an anti-cancer factor and CDK5RAP3 is a pro-cancer factor in PCa, and that the expressions of both were significantly correlated with the clinic-pathologic features." (PMID 38643190, 2024). "All genes, except for ERLIN2, came from the MAPK family signaling cascade, which is an important therapeutic target in cancer." (PMID 37627118, 2023). "First, the analysis of TCGA RNA-seq data using the TIMER database showed that ERLIN2 mRNA expression was significantly higher in LUAD and some other cancers." (PMID 33424830, 2020). "Similarly, DHA down-regulated genes potentially associated to a low OS rate and poor prognosis in GBM such as ERLIN2 and TMEM41B that can inhibit cancer cell growth and metastasis." (PMID 38429759, 2024).
tumor (9 papers, 2012 to 2024). "Through the xCELL algorithm, this study found that ERLIN2 and CDK5RAP3 were significantly associated with many tumor-immune cells." (PMID 38643190, 2024). "Thus, ERLIN2 could facilitate a cytoprotective response to various cellular stresses associated with oncogenesis, although the molecular mechanisms by which ERLIN2 coordinates ER pathways in breast carcinogenesis remain unclear." (PMID 34572057, 2021). "ERLIN2 knockdown markedly inhibited the growth rate of the tumor cells and reduced other malignant tumor cell behaviors, such as clonogenic survival, colonies counting, and capability for DNA replication." (PMID 33424830, 2020). "To explore the role of ERLIN2 in the development of LUAD, we first analyzed the expression levels of ERLIN2 in 10 pairs of fresh tumor tissues and matched normal tissues using Western blotting and qPCR." (PMID 33424830, 2020). "Although these studies have indicated that ERLIN2 is critically involved in both tumor development and childhood motor neuron degeneration, the role and mechanism of ERLIN2 in pathophysiology remain poorly understood." (PMID 27462423, 2015). "ERLIN2 protein signals are mainly distributed to the deranged invasive tumor tissues derived from mammary gland epithelial cells." (PMID 27462423, 2015). "The staining intensities of ERLIN2 were significantly higher in tumor cells than in normal tissue cells (P = 0.001)." (PMID 22681620, 2012). "In addition, ERLIN2 expression significantly correlates with several tumor-infiltrating immune cells, particularly naive B cells and neutrophils." (PMID 33424830, 2020). "ERLIN2 was abnormally expressed in a variety of tumor tissues and is highly expressed in LUAD." (PMID 33424830, 2020). "ERLIN2 was also highly expressed in 129 of 284 (45.4%) lung-tumor tissues." (PMID 33424830, 2020). "In our study, CIBERSORT analysis suggested that the expression levels of ERLIN2 had a significant effect on the infiltration levels of naive B cells and neutrophils in the LUAD tumor microenvironment." (PMID 33424830, 2020). "Despite the CNV, no further methylation defect of ERLIN 2 was detectable in the tumor, likely because of the constitutional hypomethylation affecting this DNA region." (PMID 37046605, 2023). "Many genes in these chromosome regions, such like ERLIN2 (amp 8p11.23), VAV2 (del 9q34.2), ADAMTS6 (del 5q12.3) and NCS1 (del 9q34.11), are known to be related with tumor invasion and metastasis." (PMID 33193655, 2020).
infection (3 papers, 2017 to 2025). The state of being infected such as from the introduction of a foreign agent such as serum, vaccine, antigenic substance or organism. "Importantly, as reconstituting either Erlin1 or Erlin2 fully restored the infection block caused by silencing Erlin1/2, these related membrane proteins likely execute overlapping functions during SV40 infection." (PMID 28614383, 2017). "While depleting either Erlin1 or Erlin2 individually blocked infection moderately (compare second and third to first bar), simultaneous knockdown of Erlin1/2 potently reduced SV40 infection (compare fourth to first bar)." (PMID 28614383, 2017). "Within this report we have extended our list of host proteins co-localizing within the WNVKUN RC and show that two host proteins known to associate with “lipid raft-like,” cholesterol-rich domains within the ER, erlin-1 and erlin-2, co-locate with dsRNA during infection." (PMID 34055786, 2021). "Interestingly, Mic60/IMMT, CKAP4, and Erlin2 were primarily present in the pull-downs of Sne-infected samples expressing FLAG-tagged SneRING, indicating that active infection is necessary for the interactions with SneRING to take place." (PMID 41196921, 2025).
ERLIN2 also shares sentences with these, for which no sentence is quoted: asthma (1 paper); breast (1); cerebellar ataxia (1); dementia (1); esophageal carcinoma (1); glioma (1); head and neck cancer (1); hepatitis C virus infection (1); hepatoma (1); intraductal carcinoma (1); invasive breast carcinoma (1); leukemia (1); lung squamous cell carcinoma (1); mucinous carcinoma (1); nasopharyngeal carcinoma (1); pancreatic cancer (1); papillary carcinoma (1); pseudobulbar palsy (1); scoliosis (1); Seizure (1); Spastic tetraparesis (1); stomach adenocarcinoma (1); thyroid carcinoma (1); type 1 diabetes mellitus (1); uterine corpus endometrial carcinoma (1); uveal melanoma (1).